CRY1 (cryptochrome circadian regulator 1)
Description:
Transcriptional repressor which forms a core component of the circadian clock. The circadian clock, an internal time-keeping system, regulates various physiological processes through the generation of approximately 24 hour circadian rhythms in gene expression, which are translated into rhythms in metabolism and behavior. It is derived from the Latin roots 'circa' (about) and 'diem' (day) and acts as an important regulator of a wide array of physiological functions including metabolism, sleep, body temperature, blood pressure, endocrine, immune, cardiovascular, and renal function. Consists of two major components: the central clock, residing in the suprachiasmatic nucleus (SCN) of the brain, and the peripheral clocks that are present in nearly every tissue and organ system. Both the central and peripheral clocks can be reset by environmental cues, also known as Zeitgebers (German for 'timegivers'). The predominant Zeitgeber for the central clock is light, which is sensed by retina and signals directly to the SCN. The central clock entrains the peripheral clocks through neuronal and hormonal signals, body temperature and feeding-related cues, aligning all clocks with the external light/dark cycle. Circadian rhythms allow an organism to achieve temporal homeostasis with its environment at the molecular level by regulating gene expression to create a peak of protein expression once every 24 hours to control when a particular physiological process is most active with respect to the solar day. Transcription and translation of core clock components (CLOCK, NPAS2, BMAL1, BMAL2, PER1, PER2, PER3, CRY1 and CRY2) plays a critical role in rhythm generation, whereas delays imposed by post-translational modifications (PTMs) are important for determining the period (tau) of the rhythms (tau refers to the period of a rhythm and is the length, in time, of one complete cycle). A diurnal rhythm is synchronized with the day/night cycle, while the ultradian and infradian rhythms have a period shorter and longer than 24 hours, respectively. Disruptions in the circadian rhythms contribute to the pathology of cardiovascular diseases, cancer, metabolic syndromes and aging. A transcription/translation feedback loop (TTFL) forms the core of the molecular circadian clock mechanism. Transcription factors, CLOCK or NPAS2 and BMAL1 or BMAL2, form the positive limb of the feedback loop, act in the form of a heterodimer and activate the transcription of core clock genes and clock-controlled genes (involved in key metabolic processes), harboring E-box elements (5'-CACGTG-3') within their promoters. The core clock genes: PER1/2/3 and CRY1/2 which are transcriptional repressors form the negative limb of the feedback loop and interact with the CLOCK|NPAS2-BMAL1|BMAL2 heterodimer inhibiting its activity and thereby negatively regulating their own expression. This heterodimer also activates nuclear receptors NR1D1/2 and RORA/B/G, which form a second feedback loop and which activate and repress BMAL1 transcription, respectively. CRY1 and CRY2 have redundant functions but also differential and selective contributions at least in defining the pace of the SCN circadian clock and its circadian transcriptional outputs. More potent transcriptional repressor in cerebellum and liver than CRY2, though more effective in lengthening the period of the SCN oscillator. On its side, CRY2 seems to play a critical role in tuning SCN circadian period by opposing the action of CRY1. With CRY2, is dispensable for circadian rhythm generation but necessary for the development of intercellular networks for rhythm synchrony. Capable of translocating circadian clock core proteins such as PER proteins to the nucleus. Interacts with CLOCK-BMAL1 independently of PER proteins and is found at CLOCK-BMAL1-bound sites, suggesting that CRY may act as a molecular gatekeeper to maintain CLOCK-BMAL1 in a poised and repressed state until the proper time for transcriptional activation. Represses the CLOCK-BMAL1 induced transcription of BHLHE40/DEC1. Represses the CLOCK-BMAL1 induced transcription of ATF4, MTA1, KLF10 and NAMPT (By similarity). May repress circadian target genes expression in collaboration with HDAC1 and HDAC2 through histone deacetylation. Mediates the clock-control activation of ATR and modulates ATR-mediated DNA damage checkpoint. In liver, mediates circadian regulation of cAMP signaling and gluconeogenesis by binding to membrane-coupled G proteins and blocking glucagon-mediated increases in intracellular cAMP concentrations and CREB1 phosphorylation. Inhibits hepatic gluconeogenesis by decreasing nuclear FOXO1 levels that down-regulates gluconeogenic gene expression (By similarity). Besides its role in the maintenance of the circadian clock, is also involved in the regulation of other processes. Represses glucocorticoid receptor NR3C1/GR-induced transcriptional activity by binding to glucocorticoid response elements (GREs). Plays a key role in glucose and lipid metabolism modulation, in part, through the transcriptional regulation of genes involved in these pathways, such as LEP or ACSL4 (By similarity). Represses PPARD and its target genes in the skeletal muscle and limits exercise capacity (By similarity). Plays an essential role in the generation of circadian rhythms in the retina (By similarity). Represses the transcriptional activity of NR1I2 (By similarity).
Synonyms: PHLL1; DSPD
Tractability: Small molecule: a high-quality ligand is known. PROTAC: UniProt records ubiquitination sites on it; ubiquitination databases record sites on it; a small molecule that binds it is known.
Gene: Protein-coding gene on chromosome 12 (106,991,364 to 107,093,855, reverse strand). Ensembl gene ENSG00000008405.
Subcellular location: Cytoplasm; Nucleus
Subcellular location (Human Protein Atlas): Microtubules; Nuclear membrane; Nucleoplasm
Pathways (Reactome):
Circadian clock: Degradation of CRY and PER proteins; Phosphorylated BMAL1:CLOCK (ARNTL:CLOCK) activates expression of core clock genes; Phosphorylation and nuclear translocation of the CRY:PER:kinase complex; Phosphorylation of CLOCK, acetylation of BMAL1 (ARNTL) at target gene promoters; The CRY:PER:kinase complex represses transactivation by the BMAL:CLOCK (ARNTL:CLOCK) complex
Gene Ontology:
Molecular function: deoxyribodipyrimidine photo-lyase activity; DNA (6-4) photolyase activity; double-stranded DNA binding; nuclear receptor binding; phosphatase binding; protein binding; blue light photoreceptor activity; DNA binding; DNA-binding transcription factor binding; E-box binding; histone deacetylase binding; kinase binding; protein kinase binding
Biological process: negative regulation of DNA-templated transcription; negative regulation of transcription by RNA polymerase II; blue light signaling pathway; circadian regulation of gene expression; circadian rhythm; entrainment of circadian clock by photoperiod; gluconeogenesis; glucose homeostasis; negative regulation of circadian rhythm; negative regulation of G protein-coupled receptor signaling pathway; negative regulation of gluconeogenesis; negative regulation of nuclear receptor-mediated glucocorticoid signaling pathway; negative regulation of protein ubiquitination; positive regulation of protein ubiquitination; regulation of circadian rhythm; regulation of DNA damage checkpoint; response to activity; response to glucagon; response to light stimulus; signal transduction in response to DNA damage; lipid storage; negative regulation of glucocorticoid secretion; positive regulation of gluconeogenesis; regulation of gluconeogenesis; response to insulin
Cellular component: nucleoplasm; nucleus; cytoplasm; mitochondrion
Genetic constraint (gnomAD): Loss-of-function variants: 41 observed, 72.54 expected, observed/expected ratio (o/e) 0.57, 90% interval 0.44 to 0.73. The upper end of that interval is the gene's LOEUF score, 0.73, which puts it in group 3 of 6, group 1 being the genes least tolerant of losing a copy. Missense variants: 555 observed, 703.68 expected, observed/expected ratio (o/e) 0.79, 90% interval 0.74 to 0.85. Synonymous variants: 235 observed, 240.43 expected, observed/expected ratio (o/e) 0.98, 90% interval 0.88 to 1.09.
Homologues: Orthologues: chimpanzee CRY1 (99% identical), macaque CRY1 (99% identical), dog CRY1 (99% identical), pig CRY1 (98% identical), mouse Cry1 (96% identical), rabbit CRY1 (94% identical), guinea pig CRY1 (92% identical), rat Cry1 (92% identical), tropical clawed frog cry1 (91% identical), zebrafish cry1a (84% identical), zebrafish cry1b (80% identical). Paralogues in human: CRY2 (72% identical).
Diseases named in the same sentence as CRY1 in open-access papers:
CRY1 is named in the same sentence as 137 diseases in open-access papers, as found by Europe PMC text mining. Sharing a sentence is not in itself a finding about the gene and the disease. The quoted sentences say what the papers report.
Obesity (26 papers, 2014 to 2025). Accumulation of substantial excess body fat. "Research has shown that CRY1 is associated with components of metabolic syndrome, such as hypertension and triglyceride levels, as well as obesity and insulin resistance (IR)." (PMID 39104759, 2024). "Evidence suggests a potential association between CRY1 (rs10861688) polymorphism, obesity and related cardiovascular risk factors." (PMID 39104759, 2024). "A study on mice found that CRY1 deficiency had an interaction with the high-fat diet and can lead to increased obesity as a result of increased insulin and accumulation of fat in white adipose tissue." (PMID 37580741, 2023). "This cross-sectional study examined the interaction between the AHEI and CRY1 gene polymorphism on CVDs risk factors in overweight women and women with obesity." (PMID 37580741, 2023). "In the present study, we investigated the interaction between HBI and BMI-GRS, including MC4R (rs17782313), CAV-1 (rs38 07992), and Cry1 (rs2287161) on abdominal obesity and markers for metabolically associated obesity status in overweight and obese women." (PMID 36167582, 2022). "In the Cry1/Cry2 double-deficient mouse, enhanced vulnerability to diet-induced obesity and metabolic syndrome has been demonstrated." (PMID 26000016, 2015). "According to some studies, diet can be interaction with CRY1 polymorphism and may be related to obesity and the risk of cardiovascular diseases (CVD)." (PMID 37580741, 2023). "Some studies showed a high-fat diet, high-salt diet, or low-carbohydrate and high-protein diet may have an interaction with CRY1 gene variation for obesity and CVDs risk factor." (PMID 37580741, 2023). "Also, a research showed that high fat diet can influence mice with CRY1 deficiency and induct resistance to obesity." (PMID 37580741, 2023). "According to our knowledge, there are no comparable studies that compare HBI and markers such as MC4R (rs17782313), CAV-1 (rs3807992), and Cry-1 (rs2287161) with abdominal obesity and obesity-related metabolic risk factors in overweight and obese women across time." (PMID 36167582, 2022). "Also, Cry − 1 has an important role in metabolism and the C-allele of the Cry-1 polymorphism can lead to significantly higher obesity indices such as BMI, weight, WC, and hip circumferences." (PMID 36324080, 2022). "HFD can accelerate the degradation of Cry1 and induce obesity-associated hyperglycemia." (PMID 31139087, 2019). "HFD can accelerate the degradation of Cry1 and induce to obesity-associated hyperglycemia." (PMID 31139087, 2019). "Besides, previous studies show the CRY1 variant is associated with obesity and insulin resistance." (PMID 34610814, 2021). "In this study, the interaction between CRY1 polymorphism and alternative healthy eating index (AHEI) on cardiovascular risk factors in overweight women and women with obesity was investigated." (PMID 37580741, 2023). "The deletion of Cry1/2 results in behavioral and molecular circadian arrhythmicity and increased vulnerability to high-fat-diet-induced obesity, which is mediated by increased insulin secretion and lipid storage in adipose tissues in Cry1/2(-/-) mice." (PMID 37626963, 2023). "So, this study examined the interaction between CRY1 polymorphism and AHEI on cardiovascular risk factors in overweight women and women with obesity." (PMID 37580741, 2023). "In conclusion, these findings suggest that macronutrient intake patterns were associated with obesity susceptibility, and the associations were different depending on the circadian clock genotypes of the CLOCK, PER2, and CRY1 loci." (PMID 35276838, 2022). "Obesity resulted in overall disruption of core clock genes (i.e., Bmal1, Clock, Rev-erbα/Nr1d1, Rev-erbβ/Nr1d2, Per1, Per2, Cry1, Cry2, Dbp and Rorα) in WAT." (PMID 35198059, 2022). "After stratification by the genotypes of nine SNPs, the obesity risk according to the patterns was different according to the genetic variants of CLOCK, PER2, and CRY1." (PMID 35276838, 2022).
Obesity (continued). "This cross-sectional study investigated the relationship of genetic risk score by obesity-related genetic markers, including MC4R (rs17782313), CAV-1 (rs3807992), and Cry-1 (rs2287161), with cardiometabolic risk factors in overweight and obese women." (PMID 36324080, 2022). "After the genotype stratification of nine SNPs of circadian genes, the association between the FC ratio and obesity risk differed by the genetic variants of CLOCK, PER2, and CRY1." (PMID 35276838, 2022). "In the male VLFC group, the minor allele carriers of CLOCK rs9312661, CRY2 rs7951225, and the GG genotype of CRY1 rs11113192 showed increased risks of obesity; however, significances were diminished after the Bonferroni correction." (PMID 35276838, 2022). "An interaction between CRY1 rs11113192 and the FC on obesity was observed (p-interaction = 0.009); however, the significance disappeared after multiple corrections." (PMID 35276838, 2022). "Intriguingly, the associations between macronutrient intake patterns and obesity risks were different depending on the genotypes of CLOCK rs11932595, PER2 2304672, and CRY1 rs3741892." (PMID 35276838, 2022). "With the ChIP‐Seq and mRNA microarray assays, a critical role is identified for Kdm6a in the regulation of H3k27me3 to impact the expression of Crytochrome 1 (Cry1) in the hypothalamus of diet induced obesity mice." (PMID 34306972, 2021). "Inhibition of Kdm6a restores the H3k27me3 modification, reduces the Cry1 expression in the hypothalamus, and sensitizes leptin signaling to combat obesity‐related disease." (PMID 34306972, 2021). "We found that reduction of Cry1 through H3k27me3 modification by deactivation or removal of Kdm6a improves the properties of diet‐induced obesity." (PMID 34306972, 2021). "The results show that inhibition of Kdm6a reduces the Cry1 expression and sensitizes leptin signaling to combat obesity‐related disease." (PMID 34306972, 2021). "The current cross-sectional study was conducted among women with overweight of obesity to investigate the interactions between the CRY1 gene and fat intake on RMR." (PMID 34610814, 2021). "In insulin-resistant mice, the perturbation of CLOCK, BMAL1, reduced c-erb-αoncogene (REV-ERBα) and Cryptochrome Circadian Clock 1 (CRY1) mRNA expression is evident during obesity." (PMID 33142938, 2020). "Interestingly, high-fat feeding decreased CRY1 protein expression in an autophagy-dependent manner, while restoring hepatic CRY1 reversed obesity-associated hyperglycemia, suggesting that this regulatory network is a potential attractive target for therapy of obesity-associated hyperglycemia." (PMID 30609663, 2019). "To determine whether the absence of p110α modifies core clock genes in the context of HFD-induced obesity, we assessed gene expression of Bmal1, Cry1, Per2, and Rev-erbα." (PMID 40228209, 2025). "Moreover, CRY1 contains two interaction regions that regulate its degradation to achieve diurnal blood glucose control, further affecting conditions such as obesity." (PMID 37893916, 2023). "Regarding CRY1 rs3741892, which showed a higher obesity risk in both genotypes, the GG genotype, but not the CG/CC genotype, had a greater incidence of abdominal obesity (OR: 1.90, 95% CI: 1.30–2.76, p = 0.0008)." (PMID 35276838, 2022). "CRY1 and CRY2 polymorphisms showed a significant link between diabetes and obesity." (PMID 35053018, 2021). "While our data suggest that Cry1 may be a potential novel therapeutic target to combat diet-induced obesity, future studies will be needed to determine if a pharmacological manipulation of Cry1 also prevents weight gain." (PMID 24782829, 2014). "In addition, under the VLFC condition, CRY1 rs3741892 had a significantly greater obesity risk than the reference regardless of genotype (GG genotype, OR: 1.60, 95% CI: 1.22–2.10, p = 0.0007; GA/GG genotype, OR: 1.76, 95% CI: 1.30–2.38, p = 0.0002)." (PMID 35276838, 2022).
Obesity (continued). "In the present study, conducted in a population of subjects with overweight/obesity, we observed an association between PM exposure measured in the week before the blood drawing and the methylation of circadian cycle genes (i.e., CLOCK, CRY1, CRY2, PER1, PER2, and PER3)." (PMID 33513987, 2021). "The present study aimed to evaluate the effects of PM2.5 and PM10 on the methylation profile of the clock genes ARNTL, CLOCK, CRY1, CRY2, PER1, PER2, and PER3 in a population of 200 women with obesity." (PMID 33513987, 2021). "Although several studies have assessed the interaction of CRY and diet, such as obesity, diabetes, and insulin resistance, no research has been shown to evaluate the interaction between AHEI and CRY1 polymorphism." (PMID 37580741, 2023). "This is in contrast to mice lacking only Cry1, however, that are more resistant to diet-induced obesity and show decreased overall fat mass compared to wild type controls." (PMID 26000016, 2015). "Utilizing Cry1−/− and Cry2−/− mice, we demonstrate for the first time that Cry1−/− loss interferes with HFD-induced obesity, and that the physiological basis of this effect is not related to reduced energy intake." (PMID 24782829, 2014). "In summary, these results highlight further the importance of CRY as an important regulator of energy homeostasis by showing that ablation of Cry1−/−, but not Cry2−/− is associated with relative resistance to HFD-induced obesity." (PMID 24782829, 2014). "Furthermore, ablation of Cry1, prevented HFD induced obesity in mice." (PMID 39268728, 2024). "Similarly, diet-induced obesity mice exhibited elevated expression of SREBP1c and gluconeogenic genes whereas CRY1 was not activated." (PMID 27412556, 2016). "In another study, the ablation of Cry1, but not Cry2, prevented HFD-induced obesity in mice, suggesting increased energy expenditure." (PMID 37626963, 2023). "In this study, we demonstrate that ablation of Cry1, but not Cry2, prevents high-fat diet (HFD)-induced obesity in mice." (PMID 24782829, 2014).